HIF1A (hypoxia inducible factor 1 subunit alpha)
Diseases named in the same sentence as HIF1A in open-access papers (continued):
Sharing a sentence is not in itself a finding about the gene and the disease.
Obesity (continued). "Furthermore, we evaluated the role of hypoxia-inducible factor-1 alpha (HIF-1α) in obesity-AD comorbidity, and then investigated whether it is regulated by TJT treatment." (PMID 31920651, 2019). "Therefore, we assumed HIF-1α might be the crucial factor which worsens the AD-like condition in obesity-AD comorbidity." (PMID 31920651, 2019). "We put forward the conclusion that vitamin D deficiency during pregnancy may promote the proliferation and differentiation of pre-adipocytes, which may be associated with methylation alterations of genes, such as Vldlr and Hif1α, ultimately leading to offspring obesity." (PMID 29321608, 2018). "Hence, a rise in HIF1A protein abundance supports the hypothesis that obesity during pregnancy results in placental hypoxia." (PMID 28291256, 2017). "In obesity, adipocyte hypertrophy results in decreased oxygen diffusion, leading to localized tissue AT hypoxia, as evidenced by upregulation of the hypoxia master regulator, hypoxia induced factor (HIF-1α), which stimulates MCP-1 and subsequent macrophage chemotaxis." (PMID 25360510, 2014). "Vascular endothelial growth factor (VEGF) is a downstream target of HIF‐1α whose gene expression within adipose tissue has been shown to increase with obesity and may be necessary for WAT growth, perhaps by promoting angiogenesis and preventing WAT hypoxia and attenuating inflammation." (PMID 25347855, 2014). "This study demonstrates that HIF-1α, a master regulator of oxygen homeostasis, stimulates PII-driven aromatase expression in human breast ASCs with other transcription factors, including CREB1, in response to tumor-derived and obesity-associated inflammatory mediator PGE2." (PMID 23566437, 2013). "Thus, adipose and liver HIF-1α may be an important target to address the metabolic dysfunction of obesity." (PMID 23049707, 2012). "Another study showed that inhibiting HIF-1α in adipose tissue can alleviate obesity and insulin resistance, making HIF-1α a potential therapeutic target for obesity and T2DM." (PMID 39996906, 2025). "Obesity-induced adipose hypoxia activates the hypoxia-inducible factor alpha (HIF-α) axis, where HIF-1α and HIF-2α exhibit functional antagonism: HIF-1α exacerbates insulin resistance (IR) and inflammation, whereas HIF-2α counteracts these effects." (PMID 41039626, 2025). "Hypoxia-inducible factor 1 subunit alpha (HIF1α) also plays a critical role in increasing glycolytic flux and abrogating oxidative metabolism (OXPHOS) in macrophages in obesity and T2D." (PMID 38988822, 2024). "Higher expression of ANGPT2, HIF-1a, EGFL6, several MMP genes, and GDF15 was observed in individuals living with obesity (p ≤ 0.008)." (PMID 38024342, 2023). "HIF1-α is the key regulator of VEGF expression, which gets upregulated in AT expansion during obesity." (PMID 37014444, 2023). "HIF-1α represses SIRT2 expression and promotes obesity, while SIRT2 knock-out animals develop obesity, hepatic steatosis, and ER stress." (PMID 36834782, 2023). "In obesity, a rapid expansion of AT leads to ECM remodeling and thereby persistent hypoxia, which activates HIF1-α." (PMID 37014444, 2023). "Leptin is described as another major driver in the context of obesity-induced angiogenesis, which stimulates the expression of VEGF by activating the hypoxia-inducible factor 1-alpha HIF1α and NFĸB pathways." (PMID 36010901, 2022). "Higher expression of angiopoietin-2 (ANGPT2), HIF-1α, EGF like domain multiple 6 (EGFL6), several MMP genes, and growth/differentiation factor-15 (GDF15) was observed in individuals living with obesity (P ≤ 0.008)." (PMID 35958557, 2022). "Several pathways associated with tumor progression have been found to be upregulated in HK-II high expressors (for example, the HIF1A regulation of glycolysis or IL1 and megakaryocytes in obesity,)." (PMID 35677429, 2022).
Obesity (continued). "Ceruloplasmin, a serum ferroxidase involved in copper transport, is raised in patients with obesity, and induces angiogenesis probably by stimulating VEGF-A production via the HIF1α signalling pathway." (PMID 36038791, 2022). "Nevertheless, a positive correlation between LAMP-2A and HIF-1α (a well-known CMA target) emerged only in OB placentas, suggesting a different activity of CMA in obesity." (PMID 33920886, 2021). "In early obesity, inflammatory cues in CCs were mediated by the upregulation of genes involved in cellular response to stress as DEAD-box helicase 5 (Ddx5), hypoxia inducible factor 1 subunit alpha (Hif1a), and ADAM metallopeptidase domain 9 (Adam9)." (PMID 34805147, 2021). "The close relationship between obesity and obstructive sleep apnea (OSA) is known, in which an upregulation of serum HIF-1α protein was found with a decrease after two months of continuous positive airway pressure treatment." (PMID 34829944, 2021). "Myeloid-specific deletion of HIF-1α results in decreased inflammatory signaling, decreased CLS formation and an ameliorated metabolic phenotype upon diet-induced obesity." (PMID 32140136, 2020). "Hypoxia-inducible factor 1 alpha (HIF-1α) is known to be a key regulator of a tissue’s response to hypoxia and plays a role in obesity-induced metabolic syndrome." (PMID 32085589, 2020). "Metabolic pathways most significantly enriched by the list of candidate genes include Relaxin Signaling, Leptin Signaling in Obesity, IGF-1 Signaling, PXR/RXR Activation and HIF1α Signaling pathways." (PMID 33499953, 2020). "There is one clue that HIF1α activation can exacerbate the inflammation and fibrosis status of T2DM during hypoxia, thereby elevating obesity and insulin resistance in mice." (PMID 32851081, 2020). "Adipocyte specific KO of HIF1A, inhibition of HIF-1 by acriflavine or PX-478, or adipocyte specific ARNT KO decreased obesity and insulin resistance in mice fed with high-fat diet." (PMID 30832409, 2019). "In our study, we propose a basic in vivo model of obesity-AD comorbidity through HFD/DNFB administration, and discovered HIF-1α as one of the possible links between the two diseases." (PMID 31920651, 2019). "Accordingly, transgenic mice overexpressing an adipose tissue-selective dominant negative HIF-1α mutant that decreased HIF-1 activity, developed increased obesity after high-fat diet treatment and accumulated enlarged adipocyte LDs." (PMID 30832409, 2019). "Despite a plethora of studies addressing the roles of HIFs in adipose dysfunction, the involvement of HIF-1α and HIF-2α in obesity remains controversial." (PMID 30382123, 2018). "Oxidation-sensing factor, HIF-1α, and VEGF are often discussed in the context of obesity, because cellular hypoxia has been observed in the adipose tissue of obese individuals." (PMID 28751933, 2017). "Oxygen sensor PHDs play important roles in the regulation of HIF-1α and VEGF but can become pathologically elevated in a model of obesity." (PMID 28725215, 2017). "Previous studies suggest that the prolyl hydroxylase domain (PHD) family of enzymes, which regulate HIF-1α and VEGF activity, are pathologically increased in models of obesity and type 2 diabetes mellitus (T2DM)." (PMID 28725215, 2017). "HIF-1α generally augments the production of BNP, and it is decreased in diabetic patients with obesity." (PMID 28481950, 2017). "In this study, as candidate genes we chose 1) genes related to T2DM, obesity, or insulin resistance found by previous GWAS and 2) genes related to glucose and lipid metabolism, insulin secretion, or MVCD, such as the HIF1α/-VEGF pathway." (PMID 26139146, 2015). "Consistent with this study, we also showed that knockout of PHD2 increased HIF-1α expression and reduced HFD-induced obesity." (PMID 25546437, 2014).
Obesity (continued). "RT-qPCR results showed that, compared with the control group, mRNA expression levels of VEGFA, VEGFR-2, CD31, and SIRT1 were significantly decreased in the obesity group (P < 0.001), while the expression levels of GLUT1, HIF-1α, TNF-α, IL-6, HMGB1, and TLR4 were significantly upregulated (P < 0.01)." (PMID 41505418, 2026). "HIF-1α potentially plays a prominent role in LD formation and the storage of lipids and fatty acids in the small intestine, particularly during prolonged HFD consumption or obesity." (PMID 39900792, 2025). "Adipose tissue hypoxia is well documented in individuals with obesity, and HIF1α activation occurs in hepatocytes of patients with nonalcoholic fatty liver disease, which is present in approximately 75% of individuals with obesity." (PMID 41243971, 2025). "In this study, we used in vivo and in vitro models to demonstrate that adipocyte Serpina3c inhibited Nrf2 expression to reduce Hif1α transcription, thereby reducing glycolysis and DNL, ultimately ameliorating obesity, hypertriglyceridemia, and metaflammation induced by HFD." (PMID 39693610, 2025). "In adipose tissue macrophages, macrophage‐specific HIF‐1α knockout in mice has not found that HIF‐1α plays an essential role in the activation of adipose tissue macrophages at the early stages of obesity." (PMID 40045164, 2025). "However, unlike the effect observed in VAT, sulpiride did not cause alterations in the expression of Insr, Glut4 and Hif1α, being Prlr and Glut4 the only genes downregulated in obesity, indicating that the effects of sulpiride on SAT may be mediated through different mechanisms." (PMID 38635745, 2024). "For instance, genetic Hif1α ablation in myeloid cells protects against the development of HFD-induced metabolic inflammation and insulin resistance, while macrophage HIF2α suppresses inflammation and alleviates obesity-related insulin resistance." (PMID 38509584, 2024). "Suppression of HIF1α in PDGFRβ + progenitors promotes adipogenesis within subcutaneous and intra-abdominal depots, leading to healthy WAT remodeling and improved metabolic health in obesity." (PMID 38509584, 2024). "GSEA and KEGG analysis of obesity showed an enhancement of cytokine and chemokine pathways, whereas the results of COPD showed an upregulation of repair-related genes such as cell junctions, HIF1α, and FOXO3." (PMID 37886639, 2023). "In a rodent model, diet-induced obesity increases HIF-2α but not HIF-1α in the intestine, and sleeve gastrectomy induces HIF-2α in the upper intestine." (PMID 38037591, 2023). "Furthermore, it has been reported that HIF1α inhibitor PX-478 and HIF2α inhibitors PT2385 and PT2399 prevent diet-induced obesity and liver steatosis, accompanied by an induction of thermogenic gene expression in adipose tissues." (PMID 35672324, 2022). "In this study, we found that HIF-1α mediates MCP1, TNFα, and IFNγ production and that HIF-1α-mediated impairment of liver and EWAT increases IL-1β production, which induced M1 polarization in mice contributing to obesity-induced NAFLD." (PMID 34360607, 2021). "Subjects with class III obesity (BMI > 40 kg/m2) and OHS exhibited significantly higher adipose HIF1A protein levels versus those with class I obesity (BMI 30–34.9 kg/m2) and lean controls whereas those with class III obesity without OHS showed an intermediate response." (PMID 33758342, 2021). "Interestingly, diet-induced hyperleptinemia was recently demonstrated to lead to alteration in the HIF1-α/VEGF signaling in hypothalamic astrocytes, which is in turn responsible for the obesity-induced hypertension." (PMID 34360816, 2021). "Soluble factors released from obese adipocytes lead to liver HIF1α overexpression and deletion of hepatic HIF1α protection from obesity-induced glucose intolerance, without altering BMI or insulin resistance in murine models." (PMID 32752277, 2020).
Obesity (continued). "However, adipose tissue specific HIF1-α or PHD inhibition, respectively, led to aggravation or amelioration of insulin sensitivity and obesity." (PMID 32816039, 2020). "The inflammatory markers TNF-α and hypoxia-inducible factor 1-alpha (HIF-1α) regulate apelin secretion and it is speculated that apelin has a role in anti-inflammatory pathways in obesity." (PMID 33327460, 2020). "Although we showed TJT could successfully improve the symptoms of obesity-AD comorbidity by regulating HIF-1α, the specific role of HIF-1α in the pathology of obesity-AD and the detailed regulatory mechanism of TJT require further investigation." (PMID 31920651, 2019). "HIF-1α also regulates Th17 cells outside the context of obesity, suggesting that additional mechanisms may link HIF-1 and Th17 in obesity." (PMID 31379820, 2019). "Unexpectedly, however, myeloid-specific deletion of a previously identified key regulator of glycolysis, Hif-1α, did not alleviate inflammatory activation of ATMs during the early stages of obesity." (PMID 29333574, 2018). "One possible mechanism explaining impaired regeneration of skeletal muscle in models of obesity is the involvement of the prolyl hydroxylase (PHD) domain family of enzymes that regulate vascular endothelial growth factor (VEGF) expression and hypoxia-inducible factor-1 alpha (HIF-1α)." (PMID 30258366, 2018). "Inflammatory activation of ATMs during early stages of obesity, however, appeared to be independent of HIF-1α." (PMID 29333574, 2018). "In HIF-1α knockout mice, fed on a high-fat diet, fat mass was decreased, adiponectin induced, and these mice did not develop either obesity or insulin resistance." (PMID 28607631, 2017). "The etiology that results in coincidence of lower HIF-1α and VEGF levels occurring with obesity, especially in tissue injury responses, also remains unknown." (PMID 28725215, 2017). "The results strongly supported that the deletion of HIF-1α in adipocytes, but not in macrophages, contributed to the improvement of obesity-induced adipose tissue inflammation and glucose tolerance in ahKO mice." (PMID 24705496, 2014). "Hypoxia activates the transcription factor hypoxia-inducible factor-1α (HIF-1α), which induces expression of various target genes; deletion of HIF-1α in adipocytes partially protects mice from HFD-induced obesity and insulin resistance compared with similarly fed wild-type controls." (PMID 23577240, 2013). "While the mechanism of HIF-2α upregulation by obesity and gastrectomy is not clear, the induction of HIF-1α and HIF-2α by gut-specific von Hippel-Lindau deletion improves glucose tolerance, whereas HIF-2α is dispensable for the metabolic improvement by gastrectomy." (PMID 38037591, 2023). "The presence and role of hypoxia in human obesity is not well described as reviewed by Ruiz-Odeja but stabilisation of hypoxia inducible factor-1α (HIF-1α) in hypoxia stimulates the expression of a range of genes involved in angiogenesis, glycolysis, and erythropoiesis." (PMID 35958557, 2022). "Reduced metabolic flexibility in macrophages lacking Hif-1α in expanding adipose tissue might have overruled effects on cytokine release during the development of obesity." (PMID 29333574, 2018). "The data indicate that sustained activation of PHD2 may not contribute to obesity-related reduction of HIF-1α." (PMID 25546437, 2014). "Finally, we show that targeted deletion of HIF-1α, specifically in myeloid cells, reduced ATM accumulation in the WAT of high fat diet fed mice, as well as local and systemic IL-1β production, implicating HIF-1α as a guardian of metabolic stress and inflammation in obesity." (PMID 32221369, 2020).
Obesity (continued). "An analysis of obesity-related genes revealed that patients with HIV had significantly higher expression of PAI-1 and HIF-1α (p < 0.05 in both) and not significantly different expression of GLUT1." (PMID 35246167, 2022). "Using a hypoxia-tracer, we show that HIF-1α nuclear translocation occurred both in hypoxic and non-hypoxic ATM suggesting that both hypoxic and pseudohypoxic stimuli activate HIF-1α and its target genes in ATM during diet-induced obesity." (PMID 32221369, 2020). "Although previous reports have shown that hypoxia in obesity induces HIFs and have illustrated the importance of proangiogenic responses in WAT and BAT adaptation to obesity, the involvement of HIF1α or HIF2α in this process was not clarified." (PMID 26572826, 2016).